YAP1 (Yes1 associated transcriptional regulator)
Diseases named in the same sentence as YAP1 in open-access papers (continued):
Sharing a sentence is not in itself a finding about the gene and the disease.
osteosarcoma (continued). "Furthermore, YAP or TAZ expression has been reported to be an independent predictor of poor outcome in osteosarcoma, and knockout of YAP1 inhibits proliferation in osteosarcoma cells in vitro and in vivo." (PMID 40983796, 2025). "Furthermore, the Hippo signaling pathway contributes to osteosarcoma chemoresistance, with YAP1 as a promising therapeutic target to overcome this resistance." (PMID 41009501, 2025). "In summary, USP10 positively regulates YAP1 protein expression in osteosarcoma cells." (PMID 37184153, 2023). "Hedgehog signaling activation could upregulate YAP1 expression and induce osteosarcoma development, or aid in generation of liver." (PMID 36479120, 2022). "In this study, we proposed that cirPIP5K1A could affect stemness of osteosarcoma through interacting with miR-515-5p and enhance expression of YAP1." (PMID 34774083, 2021). "Moreover, Hh signaling upregulation and Yap1 overexpression lead to aberrant lncRNA H19 expression in malignant osteosarcoma." (PMID 27685633, 2016). "Therefore, FAT10′s regulation of osteosarcoma cell growth also depends on YAP1." (PMID 39062505, 2024). "Therefore, we investigated the function of YAP1 in the EMT of osteosarcoma cells." (PMID 37184153, 2023). "Implication of the Hippo/YAP1 signalling pathway in resistance to chemotherapy across various cancers was highlighted, including GBM and osteosarcoma where it increased resistance to drugs like methotrexate and doxorubicin." (PMID 39718433, 2024). "The cooperation of YAP1 and SOX2 was detected in various cancer types, including osteosarcoma, urothelial cancer, and HNSCC (head and neck squamous cell carcinoma)." (PMID 35548450, 2021). "We further investigated the mechanisms of USP10 and YAP1 in osteosarcoma EMT, confirming that USP10 regulates YAP1 expression through altering the breakdown and ubiquitination of the downstream gene YAP1, thereby affecting the EMT and distant metastasis of osteosarcoma." (PMID 37184153, 2023). "Next, to further study whether USP10 affects YAP1 protein degradation, we knockdown or overexpression of USP10 in osteosarcoma cells and examined the impact of various expression patterns of USP10 on YAP1 protein levels in cells treated with or without MG132." (PMID 37184153, 2023). "Of note, while SOX2 is supposed to bind the 3′ untranslated portion of WWC1 mRNA in osteosarcoma, multiple SOX2 binding peaks are identified in the upper region of WWC1 in ESCC TT cells, suggesting SOX2 can regulate the Hippo‐YAP1 signaling in a context‐dependent manner." (PMID 31560173, 2019). "Overexpression of YAP1 decreased anoikis in both HOS and 143B osteosarcoma cells." (PMID 30514309, 2018).
bladder cancer (31 papers, 2016 to 2025). "The Hippo pathway and its transcriptional coactivator Yes‐associated protein 1 (YAP1) is implicated in bladder cancer tumorigenesis and resistance to therapy." (PMID 36385700, 2023). "In bladder cancer cells, metformin activates AMPKα, which promotes the degradation of Yes-associated protein 1 (Yap1), a key molecule of the Hippo pathway." (PMID 37344841, 2023). "We analyzed the relationship between RRBP1 and genes involved in bladder-cancer-associated or YAP1-mediated chemoresistance and genes." (PMID 34445467, 2021). "In contrast, YAP1 expression is associated with maintaining the stemness of bladder cancer cells." (PMID 40027190, 2025). "Yap1 also plays an important role in the development of bladder and the deregulation of Yap1 is significantly associated with the development and metastasis of human bladder cancer." (PMID 31455378, 2019). "Collectively, our bioinformatics results strongly support that the TGFΒ3/GLI2/YAP1 expression level is significantly associated with tumor-infiltrating CAFs, T cell desertion, and immunosuppressive phenotypes and is resistant to immunotherapy in bladder cancer." (PMID 40027190, 2025). "Although YAP1 expression was least significantly correlated with the level of tumor-infiltrating CAFs, its expression in the bladder cancer cohort remained predicted for poor survival." (PMID 40027190, 2025). "We started with a bioinformatics approach and identified a novel gene signature, TGFβ3/GLI2/YAP1 (the TGY) signature, significantly associated with immune evasion and therapy resistance in bladder cancer." (PMID 40027190, 2025). "In summary, our study identifies a unique TGFβ3/GLI2/YAP1 (the TGY signature) that is not only elevated in bladder cancer cells but also plays a crucial role in CAF transformation and function." (PMID 40027190, 2025). "During the progression to MIBC, increased rigidity of the extracellular matrix (ECM) enhances YAP1 activation in bladder cancer cells." (PMID 40635786, 2025). "Collectively, the bioinformatics analysis identified TGFβ3/GLI2/YAP1 as a potential target gene signature (TGY signature) in bladder cancer." (PMID 40027190, 2025). "Recent studies have further revealed that USP20 can promote bladder cancer progression by regulating the Hippo‐YAP1 signalling pathway." (PMID 41261048, 2025). "In colon or bladder cancer cells, overexpressing Yap1 induced Cox2 activation within cancer cells and triggered intrinsic resistance that was blocked by targeting Yap1 and/or Cox2 solely in cancer cells." (PMID 39468013, 2024). "In Bladder cancer, YAP1 signaling is found to drive cancer stemness and induce an immunosuppressive tumor microenvironment by influencing the infiltration of MDSCs and polarization of macrophages." (PMID 39630608, 2024). "YAP1, as reported, is highly expressed in tumors such as pancreatic ductal adenocarcinoma, colorectal, and bladder cancer, and it expedites the proliferation, migration, and invasion of cancer cells." (PMID 35172671, 2022). "But there are few reports on the roles of Yap1, the key molecule of Hippo pathway, in the metformin induced inhibition of bladder cancer (BLCA)." (PMID 31455378, 2019). "Our group recently showed that YAP1 is overexpressed in basal-type bladder cancer that has abundant stem cell phenotype." (PMID 31137841, 2019). "In summary, our study reveals that the crosstalk between AMPK and Yap1/TEAD4 plays an important role in bladder cancer inhibition by metformin and that it is a critical cell cycle regulator that downregulates CCNE1 and CCNE2 directly." (PMID 31455378, 2019). "We are wondering if the inhibitory effect of metformin on bladder cancer is fulfilled via Yap1 and exploring the related mechanism." (PMID 31455378, 2019).
bladder cancer (continued). "Several studies have shown that Yap1 was dramatically up-regulated in bladder cancer samples at both mRNA and protein level, contributing to progressive features and poor prognosis of bladder cancer, and acting as a biomarker for bladder cancer." (PMID 31455378, 2019). "It was reported that YAP1 and H19 expression levels were elevated in bladder cancer cells, and H19 expression was found to be significantly associated with YAP1 expression." (PMID 27835600, 2016). "Moreover, Pleomorphic adenoma gene like-2 (PLAGL2) facilitated bladder cancer progression via RACGAP1/RhoA GTPase/YAP1 signaling, and its proproliferative and prometastatic effects were negated by the RhoA inhibitor simvastatin." (PMID 39101139, 2024). "In bladder cancer the role of the Hippo pathway has not been thoroughly investigated, but over-expression of YAP1 was shown to be common in UC and associated with poorer prognosis." (PMID 30952872, 2019). "To test whether metformin can affect the cellular localization of Yap1 in the bladder cancer cells, we used the Immunofluorescence (IF) method for intracellular translocation processes of Yap1." (PMID 31455378, 2019). "We therefore assessed the effect of Yap1 activity on bladder cancer cells." (PMID 31455378, 2019). "Furthermore, YAP1 is overexpressed in common human malignancies such as colon, lung, ovary, esophagus and bladder cancer." (PMID 27705928, 2016). "Additionally, a study screening a small-molecule compound library to identify novel drugs targeting the Hippo pathway found that DMPCA (N-(3,4-dimethoxyphenethyl)-6-methyl-2,3,4,9-tetrahydro-1H-carbazol-1-amine) can induce phosphorylation of LATS1 and YAP1/TAZ in bladder cancer cells." (PMID 40635786, 2025). "Given its inhibitory effects on Nrf2, PI3K/AKT signaling, and potentially YAP1, TGN is a therapeutic candidate for drug-resistant bladder cancer." (PMID 40027190, 2025). "RACGAP1-mediated activation of RhoA can enhance the activity of YAP1/TAZ, thereby assisting PLAGL2 in promoting the progression of bladder cancer." (PMID 38898473, 2024). "Considering the regulatory role of YAP1/TEAD4 in KIF4A transcription in esophageal squamous cell carcinoma and the role of TEAD1 in chemoresistance of bladder cancer, we sought to investigate whether YAP1/TEAD1 is involved in KIF4A dysregulation in UBC." (PMID 37039264, 2023). "Notably, elevated NRF2 and YAP1 expressions have been shown to promote chemoresistance in bladder cancer 27, suggesting that TGN could potentially target YAP1, a member of the TGY signature identified bioinformatically." (PMID 40027190, 2025). "As the key component of Hippo signaling, we therefore suggest that the Yap1/TEAD4/CCNE1/2 could be a potential therapeutic axis in BLCA, via which metformin can be a potential candidate for the development of novel treatment strategies for human bladder cancer." (PMID 31455378, 2019).
sarcoma (31 papers, 2015 to 2025). A usually aggressive malignant neoplasm of the soft tissue or bone. "It regulates mesenchymal progenitor proliferation and differentiation by controlling the Hippo effector Yes-associated protein 1 (YAP1), which is constitutively activated in many sarcomas." (PMID 38414063, 2024). "Strikingly, YAP1 (Yes-associated protein 1) hyperactivity only induced sarcoma in activated satellite cells after i.m. injection of CTX or barium chloride, but not in quiescence." (PMID 33918045, 2021). "Recently, aberrant expression of Yes-associated protein 1 (YAP1) has been observed in a panel of sarcomas including CHS5–7, yet the precise role of YAP1 in CHS remains to be explored." (PMID 33495462, 2021). "However, unlike cell proliferation, focus formation, and anchorage-independent growth, which were restored entirely in response to overexpression of YAP1, the effect of YAP1 overexpression on CLP36 deficient sarcoma cell migration was somewhat limited." (PMID 35836803, 2022). "In conclusion, we analyzed the currently largest cohort of tumors of soft tissue and bone to identify strong nuclear expression levels as a common pattern of several sarcoma subtypes associated with a functional dependency on transcriptional YAP1/TAZ activity as specific liability in sarcoma cells." (PMID 31873172, 2019). "When these genes were activated in human mesenchymal stem cells (hMSCs), they led to different sarcoma subtypes: YAP1 activation led to undifferentiated pleomorphic sarcoma (UPS), while KRAS activation led to myxofibrosarcoma." (PMID 41123840, 2025). "On the other hand, YAP1 gene rearrangements have been reported in a wide spectrum of sarcomas, including vascular neoplasms such as epithelioid hemangioendothelioma (EHE)." (PMID 40879254, 2025). "Gene expression analysis comparing TCGA sarcoma samples with the model tumours revealed increased oxidative phosphorylation signalling in YAP1-driven tumours." (PMID 41123840, 2025).
sarcoma (continued). "In the sarcoma microenvironment, oncogenic YAP1 promotes collagen VI deposition, which opposes and reorganizes collagen I, compromises CD8+ T cell function, and impairs anti-tumor immunity." (PMID 38652549, 2024). "Our previous work has focused on mechanisms by which Yap1 impacts sarcoma cell–autonomous signaling and phenotypes such as proliferation, differentiation, and metastasis." (PMID 38652549, 2024). "Our findings implicate YAP1 inhibition, in combination with immunotherapy, as a promising approach to mitigate immune evasion in the sarcoma TME." (PMID 38652549, 2024). "Collectively, these results suggest that CLP36 plays an important role in regulation of YAP1 protein expression in sarcoma cells." (PMID 35836803, 2022). "From four likely pro-tumorigenic proteins upregulated in oligosarcoma, YAP1 appeared as the most interesting candidate due to its well-established role as tumor driver in different types of cancer including sarcomas." (PMID 34967922, 2022). "YAP1 affects the glycolytic metabolism of undifferentiated pleomorphic sarcoma through the NF-κB pathway." (PMID 34925434, 2021). "Two subsequent studies described YAP1 as a recurrent fusion partner in KMT2A-rearranged sarcomas that showed histologic features reminiscent of sclerosing epithelioid fibrosarcoma, and in some cases, low-grade fibromyxoid sarcoma." (PMID 32461620, 2020). "We also demonstrated that LIX1 regulates mesenchymal progenitor proliferation and differentiation by controlling the Hippo effector YAP1, which is constitutively activated in many sarcomas." (PMID 32633461, 2020). "To verify the effect of YAP1/TAZ inhibition on sarcoma cell growth in vivo, we deposited CME-1 cells on the chick embryo CAM." (PMID 31873172, 2019). "In a set of sarcoma cell lines, immunoblotting confirmed nuclear localization of YAP1 and TAZ, corresponding to their transcriptionally active pool." (PMID 31873172, 2019). "Suppression of YAP1/TAZ-TEAD mediated transcriptional activity significantly impaired sarcoma cell viability in vitro and in vivo." (PMID 31873172, 2019). "Additional studies with larger data sets are therefore needed to perform survival analysis for individual types of soft tissue/sarcoma to further validate the utility of YAP1/TAZ as prognostic biomarker." (PMID 31873172, 2019). "Here we show that YAP1/NF-κB, control the switch between differentiation and proliferation in sarcoma by suppressing the circadian clock and UPR." (PMID 30382078, 2018). "We previously reported that YAP1 is downregulated in sarcoma cells treated with SAHA/JQ1 in vitro and in vivo and that ectopic expression of constitutively active YAP1 (YAPS6A) can rescue ~ 40% of proliferation loss associated with treatment." (PMID 30382078, 2018). "(c) Kaplan-Meier survival analysis of miR-375, YAP1, c-Myc and Birc5 low and high sarcoma patients (log rank test)." (PMID 30514309, 2018). "Now we appreciate that aberrant YAP1 stabilization impacts these processes in muscle-derived sarcomas and potentially other contexts as well." (PMID 30382078, 2018). "Though well studied in epithelial tumors, the specific downstream effectors of YAP1 in sarcomas are still being elucidated." (PMID 30382078, 2018). "While no studies have examined the interplay of Notch and Hippo in sarcomas, overexpression of Yap1 in mouse intestinal epithelia stimulates Notch signaling and the expansion of undifferentiated progenitor cells." (PMID 26389076, 2015). "A small subset of MUC4-negative SEF-like sarcomas harbors recurrent YAP1::KMT2A fusions." (PMID 39031200, 2024).